E2F6 (E2F transcription factor 6)
Diseases named in the same sentence as E2F6 in open-access papers (continued):
Sharing a sentence is not in itself a finding about the gene and the disease.
glioma (continued). "To further evaluate E2F6 as a biomarker in GBM patients, we collected 134 GBM samples from the Chinese Glioma Genome Atlas (CGGA) RNA‐seq database with PFS (progression‐free survival) data available." (PMID 31508283, 2019). "E2F6 is a well-known transcription factor, and we were interested in whether E2F6 could regulate the transcription process of COX10-AS1, which is of great significance to further study the mechanism of COX10-AS1/miR-641/E2F6 in glioma." (PMID 34381702, 2021). "However, the role of E2F6 in glioma has never been reported." (PMID 34381702, 2021).
prostate carcinoma (8 papers, 2014 to 2022). A carcinoma that arises from epithelial cells of the prostate gland. "Based on the significant prognostic value of E2F1 and E2F6 as well as their association with tumor stage and Gleason score in prostate cancer, we generated nomograms for predicting a patient’s 1-year, 3-year and 5-year relapse-free survival." (PMID 35531101, 2022). "Recent evidence indicates that in prostate cancer, the mocetinostat, a class I selective inhibitor of the HDACs, up-regulates miR-31 with consequent loss of expression of its target E2F transcription factor 6 (E2F6), induction of apoptosis, and reduction in cancer growth." (PMID 29401683, 2018). "Similar to E2F2 and E2F4 mentioned previously, E2F6 has been reported in few prostate cancer studies." (PMID 35531101, 2022). "Subsequently, we further investigated the alteration of immune cell components in samples with altered expressions of E2F1, E2F2, E2F3, E2F5, and E2F6 in prostate cancer based on TCGA." (PMID 35531101, 2022). "Our results showed that the expression of E2F1–3, E2F5, and E2F6 was higher in prostate cancer tissues than in benign tissues." (PMID 35531101, 2022). "Given that prostate cancer is a highly heterogeneous tumor, somatic mutations of clinicopathologically significant E2Fs, including the E2F1, E2F2, E2F3, E2F5, and E2F6, were further investigated in PCa patients." (PMID 35531101, 2022). "In summary, E2F1, E2F2, E2F3, E2F5, and E2F6 were found to be correlated with the malignant progression of prostate cancer." (PMID 35531101, 2022). "These miRNAs regulate apoptosis in prostate cancer cells by targeting antiapoptotic proteins Bcl-w and E2F6 and they are downregulated in prostate cancer cell lines derived from advanced metastatic cancers." (PMID 33924671, 2021). "In an orthotopic xenograft model, we demonstrated that mocetinostat activated miR-31, decreased E2F6, induced apoptosis, and significantly reduced prostate cancer growth." (PMID 27551526, 2016). "We expressed E2F6 exogenously to determine if E2F6 can contribute to apoptosis resistance in prostate cancer cells." (PMID 27551526, 2016). "SiRNA knockdown of EZH2 increased miR-31 expression and decreased the antiapoptotic protein E2F6 (E2F transcription factor 6) (a target of miR-31), resulting in the sensitization of prostate cancer cells to docetaxel-induced apoptosis." (PMID 25341040, 2014). "The results revealed that E2F1 (p = 0.0578), E2F6 (p = 0.0551), Gleason score (p = 0.0201), and tumor stage (p = 0.0065) were correlated with the disease-free survival of prostate cancer, though the p values of E2F1 and E2F6 were slightly below the cut-off for significance." (PMID 35531101, 2022). "In prostate cancer, the expression of E2F6 is decreased under the action of moxiflostat." (PMID 36046639, 2022). "In prostate cancer, the miR-28-5p targeted E2F6 and induced apoptosis in DU-145 cells." (PMID 31921670, 2019). "Importantly, we found that mocetinostat also increased miR-31 expression, decreased E2F6, and induced apoptosis in the primary prostate cancer stem cells." (PMID 27551526, 2016). "Furthermore, mocetinostat increased miR-31 expression, and decreased E2F6 protein in the prostate cancer stem cells." (PMID 27551526, 2016). "Thus, activation of miR-31 and downregulation of E2F6 constitute an important mechanism in mocetinostat-induced apoptosis in prostate cancer." (PMID 27551526, 2016). "In another prostate cancer cell line DU-145, we also observed that siRNA knockdown of EZH2 or DZNeP treatment increased miR-31 expression and decreased E2F6." (PMID 25341040, 2014).
glioblastoma (6 papers, 2019 to 2023). The most malignant astrocytic tumor (WHO grade IV). "NFκB contributes to temozolomide (TMZ) resistance in glioblastoma through transcriptionally activating E2F6 expression." (PMID 35859118, 2022). "First, a recent work using a different CRISPRko library in glioblastoma stem cells treated with TMZ also revealed MMR genes as top gene candidates, and more recently, using U87MG and U87MG, EGFRvIII cells revealed that E2F6 controls TMZ resistance in EGFR mutates cells." (PMID 33271924, 2020). "Each of these transcription factors harbors oncogenic or tumor-promoting functions and some of them were reported to be overexpressed in cancer, including overexpression of E2F1, E2F6, FOXM1, and MYBL2 in glioblastomas." (PMID 35228525, 2022). "We observed that E2F6 knock-down in U-87 MG and U-118 MG had no impact on 4EBP1 mRNA and protein levels, eliminating E2F6 as a transcriptional regulator of EIF4EBP1 in these glioblastoma cell lines." (PMID 35228525, 2022). "Expression of E2F1 and E2F6 was previously reported to be higher in glioblastomas (using TCGA dataset) compared to non-neoplastic brain tissues, which we validated in the REMBRANDT dataset." (PMID 35228525, 2022). "Finally, we analyzed existing ChIP-sequencing (seq) data from the Encode consortium, which demonstrated direct binding of FOXM1, ETS1, E2F1, and E2F6 to the EIF4EBP1 promoter region, exon 1 and intron 1 (−1500 to +1000) in various normal and cancer cells, however not including glioblastoma cells." (PMID 35228525, 2022).
hepatocellular carcinoma (6 papers, 2022 to 2025). A malignant tumor that arises from hepatocytes. "Centromere protein U (CENPU) has been shown to accelerate the G1/S transition of hepatocellular carcinoma cell proliferation by interacting with E2F6 and affecting transcription of E2F1." (PMID 37292517, 2023). "For example, USP22 can stabilize the E2F6 stability and activate Akt pathway in hepatocellular carcinoma (HCC), leading to aggressive progression of HCC." (PMID 35692754, 2022). "Based on these findings, we propose that E2F6 is required for CENPU-mediated proliferation, migration, and cell cycle progression of hepatoma cells." (PMID 35844791, 2022).
cervical cancer (5 papers, 2015 to 2022). A primary or metastatic malignant neoplasm involving the cervix. "A recent study showed that circ-ZNF609 promoted cervical cancer progression as an oncogene via the regulating E2F transcription factor 6 through competitively binding to microRNA-197-3p." (PMID 35135416, 2022). "For example, circ-LRP6 functioned as an oncogenic regulator in esophageal squamous cell carcinoma by targeting the miR-182/Myc signaling and circ-ZNF609 facilitated the development of cervical cancer through the miR-197-3p-mediated E2F6 upregulation." (PMID 34057019, 2021). "Furthermore, circular RNA ZNF609 functions as a ceRNA in regulating E2F transcription factor 6 by targeting microRNA-197-3p to promote cervical cancer progression." (PMID 34288804, 2021). "In cervical cancer, gastric carcinoma proliferation enhancing transcript 1 (GHET1) regulates AKT/mTOR and Wnt/β-catenin signaling pathways by stabilizing the interaction of E2F6 and IGF2BP2." (PMID 32391379, 2020).
gastric cancer (5 papers, 2020 to 2024). A primary or metastatic malignant neoplasm involving the stomach. "Mechanistically, CRNDE was downregulated by E2F6, a generally accepted transcriptional repressor, thereby inducing autophagy and promoting chemoresistance in gastric cancer." (PMID 36046639, 2022). "Finally, we analysed the relationship between E2F6 expression and the prognosis of patients with gastric cancer using the bioinformatics database KM Plotter." (PMID 36046639, 2022). "Meanwhile, E2F6 suppresses Dnmt3b recruitment to mediate germ-line gene silencing in murine somatic tissues, and downregulates MIR22HG and lncRNA CASC2 participating in laryngocarcinoma and gastric cancer progression, respectively." (PMID 39767802, 2024).
lung adenocarcinoma (5 papers, 2009 to 2024). A carcinoma that arises from the lung and is characterized by the presence of malignant glandular epithelial cells. "Upon searching published papers and the LncMap database, we identified that five TFs—DDX17, STAT1, PPARG, ETS1, and E2F6—were closely associated with adenocarcinoma of the lung and HCG23." (PMID 32322582, 2020). "However, only over-expression of E2F6 has been associated with the development of adenocarcinoma of the lung." (PMID 32322582, 2020). "The loss of MGA in lung adenocarcinoma cells, which occurs in ~8% of lung adenocarcinoma patients, was shown to lead to an upregulation of MYC- and E2F6-target genes, resulting in an increase in cancer cell proliferation and invasiveness." (PMID 38454121, 2024). "The results indicated that the expression levels of E2F1, E2F2, E2F3, E2F5, E2F6, E2F7, and E2F8 were higher in lung adenocarcinoma and squamous cell lung carcinoma tissues than in lung tissues, whereas and the expression level of E2F4 was lower in the former than in the latter." (PMID 29754146, 2018). "Complex effects on rRNA transcription, both positive and negative, have been ascribed to E2F1, E2F4, and E2F6, when studied in transfected human lung adenocarcinoma H358 cells." (PMID 19838300, 2009). "Our results suggest that overexpression of HMGA1, E2F6, IRF1, and TFDP1 and downregulation or no expression of SUV39H1, RBL1, and HNRPD in blood is suitable for diagnosis of lung adenocarcinoma and squamous cell carcinoma sub-types of NSCLC." (PMID 24564251, 2013).
lung cancer (5 papers, 2013 to 2025). A malignant neoplasm involving the lung. "We selected seven genes [4 unique genes (E2F6, TFDP1, SUV39H1, and HNRPD) for NSCLC and 3 genes (RBL1, IRF1, and HMGA1) for general events] for validation as diagnostic markers in lung cancer." (PMID 24564251, 2013). "Interestingly, repression of E2F6 by hypoxia was also observed in lung cancer cells, and the inhibitory effect of E2F6 on LINC01436 expression was relieved under hypoxia." (PMID 30614188, 2019). "First, we investigated whether E2F6 was affected by hypoxia in lung cancer cells." (PMID 30614188, 2019). "Analysis of our gene expression profiling studies and chromatin occupancy in mouse and human lung cancer models reveals a strong enrichment for E2F4 and E2F6 targets amongst genes bound by and regulated by MGA." (PMID 34236315, 2021). "It is also found from the interaction map that E2F6 inhibition by two upregulated pro-oncomiRs (miR-28 and miR-193) is not sufficient, as the E2F6 was found to be upregulated in lung cancer." (PMID 24564251, 2013). "Additionally, downregulation of RB1 in lung cancer is not able to repress TFDP1 activity, and therefore, in lung cancer, tumorigenesis is mediated through upregulation of E2F6 and TFDP1." (PMID 24564251, 2013).
liver cancer (4 papers, 2023 to 2025). An epithelial or non-epithelial malignant neoplasm that arises from the liver. "It was found that rtcisE2F acts as a scaffold to promote the interaction between IGF2BP2 and E2F6/E2F3 mRNAs, thereby maintaining their stability and driving the self-renewal of liver cancer cells." (PMID 41155268, 2025). "By maintaining the stability of E2F transcription factor 6 (E2F6)/ E2F transcription factor 3 (E2F3), IGF2BP2 facilitates the stem cell self-renewal of liver cancer." (PMID 37554271, 2023).
osteosarcoma (4 papers, 2009 to 2023). A usually aggressive malignant bone-forming mesenchymal neoplasm, predominantly affecting adolescents and young adults. "PHC3 (polyhomeotic homolog 3), a component of the hPRC-H complex, associates with E2F6 during G0 and is lost in osteosarcoma tumors." (PMID 20015385, 2009). "For example, LINC00607 is upregulated in osteosarcoma and its knockdown suppresses osteosarcoma cell growth, invasion, and migration via completely binding to miR-607 and downregulating E2F transcription factor 6 expression." (PMID 37333453, 2023).
colon cancer (3 papers, 2016 to 2022). "Up to now, there were no studies on the role of E2F6 in colon cancer published, which was consistent with our bioinformatic analysis, as evidenced by the undifferentiated expression levels of E2F6." (PMID 32117628, 2020).
dilated cardiomyopathy (3 papers, 2017 to 2023). Cardiomyopathy which is characterized by dilation and contractile dysfunction of the left and right ventricles. "In-vivo, forced E2F6 overexpression was associated with cardiac remodeling and dilated cardiomyopathy." (PMID 36555856, 2022). "We previously examined the contribution of the E2F pathway in post-natal mouse myocardium by cardiac specific expression of E2F6 which led to the early-onset of dilated cardiomyopathy (DCM) without hypertrophy or apoptosis." (PMID 28085920, 2017).
gastric adenocarcinoma (3 papers, 2021 to 2024). "Down-regulated E2F6 in gastric adenocarcinoma is considered as an aggressive phenotype." (PMID 38221932, 2024). "A relatively high E2F6 mRNA level has been found in gastric adenocarcinoma with no lymph node metastasis, and low expression of E2F6 in gastric adenocarcinoma could be considered an aggressive phenotype." (PMID 34532281, 2021).
renal cell carcinoma (3 papers, 2019 to 2021). "In renal cell carcinoma, miR-425 suppresses cell proliferation and induces apoptosis by targeting E2F6." (PMID 32536825, 2020). "documented that E2F6 is involved in miR-425-mediated growth renal cell carcinoma." (PMID 34381702, 2021). "Hsa-mir-425 can also inhibit cell proliferation of renal cell carcinoma by targeting E2F6." (PMID 31380150, 2019).
colorectal cancer (2 papers, 2026). A primary or metastatic malignant neoplasm that affects the colon or rectum. "Finally, we observed enrichment in tyrosine kinase (TK) and E2F6 pathways, both linked to colorectal cancer progression and favorable responses to immune checkpoint blockade." (PMID 41550766, 2026).
endometrial carcinoma (2 papers, 2017 to 2020). A malignant tumor arising from the epithelium that lines the cavity of the uterine body. "In summary, this study indicates that miR-424 acts as a tumor suppressor by targeting E2F6 in endometrial cancer and simultaneously suppresses the progress of cell EMT, invasion and migration." (PMID 29371986, 2017). "Also, E2F6 was an oncogene in multiple cancers such as endometrial carcinoma." (PMID 31682716, 2020).
esophageal cancer (2 papers, 2025). A primary or metastatic malignant neoplasm involving the esophagus. "These exosomes carry LINC01592 into esophageal cancer (EC) cells, where LINC01592 directly binds to E2F6 and promotes E2F6 entry into the nucleus." (PMID 41294803, 2025).
pancreatic cancer (2 papers, 2018). "miR-193a accelerated pancreatic cancer cell cycle and stimulated cell proliferation and repopulation through inhibiting TGF-β2/TGF-βRIII/SMADs/E2F6/c-Myc signaling, and even destroyed normal intercellular junctions and promoted metastasis via repressing TGF-β2/TGF-βRIII/ARHGEF15/ABL2 pathway." (PMID 29433538, 2018).
triple-negative breast carcinoma (2 papers, 2017 to 2019). An invasive breast carcinoma which is negative for expression of estrogen receptor (ER), progesterone receptor (PR), and human epidermal growth factor receptor 2 (HER2). "It was shown to suppress tumour proliferation in triple-negative breast cancer by directly targeting E2F6 and DNTM1 and by simultaneously upregulating BRCA112." (PMID 28600498, 2017). "Furthermore, expression of a potential negative regulator of E2F6 microRNA-185 (miR-185) is downregulated in triple-negative breast cancer (i.e. negative for estrogen ER, progesterone PgR, and human epidermal growth factor receptor HER2/ERBB2) and associated with poor prognosis." (PMID 31768102, 2019).
B-cell lymphomas (1 paper, 2016). "This also offers a novel therapeutic target in E2F6 for targeted killing of EBV-associated B-cell lymphomas." (PMID 27548379, 2016).
breast adenocarcinoma (1 paper, 2019). "We tested the expression levels of E2F6 by qPCR on an array of 43 breast adenocarcinoma cDNAs and 5 normal breast cDNAs." (PMID 31768102, 2019).
Burkitt lymphoma (1 paper, 2016). A rare form of malignant mature B-cell non-Hodgkin lymphoma. "In addition, the up-regulation of E2F6 expression was also observed from the naturally isolated Burkitt's lymphoma cells Mutu Type III (latency III) when compared with Mutu Type I (latency I)." (PMID 27548379, 2016).
dependence (1 paper, 2018). "Also, we identified that Phenacetin and Buspirone could target 11 and 4 heroin-induced dependence-associated DEGs, respectively, and that Meclofenoxate could target E2F6 which had the highest dependence score also after heroin exposure." (PMID 30403753, 2018).
diabetes (1 paper, 2024). "E2F6 has been reported to repress growth-associated apoptosis of human hematopoietic progenitor cells, and to inhibit islet beta cell proliferation and participate in the pathological process of type I and II diabetes." (PMID 39767802, 2024).
Ewing sarcoma (1 paper, 2020). A small round cell tumor that lacks morphologic, immunohistochemical, and electron microscopic evidence of neuroectodermal differentiation. "A former study has shown that E2F6 could regulate both AKT/mTOR and Wnt/β-catenin pathways in Ewing’s sarcoma." (PMID 31682716, 2020). "Importantly, it has been proved that E2F6 could regulate both AKT/mTOR and Wnt/β-catenin pathways in Ewing’s sarcoma." (PMID 31682716, 2020). "E2F6 could regulate AKT/mTOR and Wnt/β-catenin pathways in Ewing’s sarcoma." (PMID 31682716, 2020).
heart failure (1 paper, 2017). Inability of the heart to pump blood at an adequate rate to meet tissue metabolic requirements. "We reveal BDH1 expression as an early biomarker of heart failure and its potential impact, through ketone signaling, on CX-43 levels in E2F6-induced DCM." (PMID 28085920, 2017). "E2F6-Tg mice display an early reduction in connexin-43(CX-43) and reduced conductivity which is a hallmark of DCM and heart failure." (PMID 28085920, 2017).
lactic acidosis (1 paper, 2010). Metabolic acidosis characterized by the accumulation of lactate in the body. "Among clusters of genes repressed by lactic acidosis in the later time points is a large group whose expression is closely linked to cell proliferation (cyclin D, PCNA, CCRK, E2F3, and E2F6)." (PMID 20844768, 2010).
leukemia (1 paper, 2018). A malignant (clonal) hematologic disorder, involving hematopoietic stem cells and characterized by the presence of primitive or atypical myeloid or lymphoid cells in the bone marrow and the blood. "In K562, the transcription factor E2F6, which might function as a repressor, is enriched in K562 single enhancers, while transcription factors STAT5, TAL1 and GATA2, which are all associated with growing culture and differentiation of leukemia cell, are significantly enriched in redundant enhancers." (PMID 30563465, 2018).
lymph node metastasis (1 paper, 2021). "Similarly, univariate analysis showed that the expression of E2F6 was negatively correlated with lymph node metastasis, suggesting that E2F6 might suppress the metastasis of GC." (PMID 34136392, 2021). "E2F6 was localized in the nucleus, and was at high levels in gastric adenocarcinoma without lymph node metastasis." (PMID 34136392, 2021).
malignant melanoma (1 paper, 2022). "Downregulation of the E2F family of transcription factors except E2F6 was reported in studied malignant melanoma cell lines along with a time-dependent decrease in cyclin A, cyclin D3, cyclin E, cdk2, cdk4, and cdc2 expressions." (PMID 36362950, 2022).